RNU6-1087P (RNA, U6 small nuclear 1087, pseudogene)
Gene: Small nuclear RNA gene on chromosome X (35,594,173 to 35,594,273, forward strand). Ensembl gene ENSG00000252411.
Homologues: Orthologues: chimpanzee U6 (94% identical). Paralogues in human: RNU6-436P (72% identical), RNU6-46P (72% identical), RNU6-1099P (71% identical), RNU6-1117P (71% identical), RNU6-1318P (71% identical), RNU6-214P (71% identical), RNU6-38P (71% identical), RNU6-641P (71% identical), RNU6-80P (71% identical), RNU6-854P (71% identical), RNU6-1011P (70% identical), RNU6-1125P (70% identical), and 1287 more.